CCR7 (C-C motif chemokine receptor 7)
Diseases named in the same sentence as CCR7 in open-access papers (continued):
Sharing a sentence is not in itself a finding about the gene and the disease.
head and neck cancer (6 papers, 2007 to 2025). A primary or metastatic malignant neoplasm affecting the head and neck. "Recently, CCR7 was associated with recurrence, gender, smoking habit and bad prognosis in head and neck cancer." (PMID 31011147, 2019). "CCR7 expression is often associated with more aggressive head and neck cancers with poor prognosis." (PMID 35203305, 2022). "Inhibition of CCR7 blocked another small GTPase, Rac, with concomitant decreased actin polymerization and reduced head and neck cancer migration, further indicating an important role for CCR7 in actin dynamics and cell migration." (PMID 35203305, 2022). "Several studies have investigated the expression and role of CCR7 in general head and neck cancer tissues and cell lines." (PMID 35203305, 2022). "CCR7 expression was investigated under normoxic or hypoxic conditions in several head and neck cancer cell lines growing in vitro as monolayers or 3D spheroids, or in vivo after xenografting into Balb/c mice." (PMID 35203305, 2022). "In head and neck cancers, another miRNA member of the let 7 family, hsa-let-7e-5p reduced CCR7 levels; conversely, inhibition of hsa-let-7e-5p increased CCR7 expression and elevated cell proliferation, migration and invasion." (PMID 35203305, 2022). "Prior studies have documented the role of phosphatidylinositol 3-kinase (PI3K) and its downstream mediator protein kinase B (AKT) in the survival and invasiveness of head and neck carcinoma cells through CCL21/CCR7 interaction." (PMID 25744065, 2015). "However, some studies have shown that high expression of CCR7 improves the prognosis of patients with head and neck cancer." (PMID 40145017, 2025). "In head and neck cancers, CCL19/CCR7 activation produced phosphorylation of mTOR that elevated cell survival." (PMID 35203305, 2022). "Since CCR7 signalling in normal immune cells mediates a pro-survival signal through the PKB/AKT cascade, it is also possible that this pathway may influence outcome in response to treatment in head and neck cancers." (PMID 17687340, 2007).
lung adenocarcinoma (6 papers, 2021 to 2025). A carcinoma that arises from the lung and is characterized by the presence of malignant glandular epithelial cells. "It has also been found that CXCR3 is expressed in lung adenocarcinoma cell lines, which suggests CCR7 and CXCR3 play a role in lung adenocarcinoma metastasis to lymph nodes." (PMID 39083441, 2025). "Given the apparent necessity of HAI-1 for M1 polarization, we next evaluated 20 human lung adenocarcinoma samples for expression of HAI-1 or CCR7 by immunohistochemistry." (PMID 34185790, 2021). "CCL19, along with CCR7, acted as clinically prognostic factors in lung adenocarcinoma." (PMID 35550569, 2022). "Additionally, elevated CCL19 was a good prognostic factor in lung adenocarcinoma patients, suggesting that CCR7/CrkL interactions are variable and might be tumor type specific." (PMID 35203305, 2022). "In a study aimed at investigating the interactions between CrkL and non-receptor kinase, c-ABL and CCR7 in surgically resected lung adenocarcinoma from 120 patients, high CCR7 mRNA expression paralleled expressions of CrkL and c-ABL and was indicative of a better prognosis." (PMID 35203305, 2022).
pulmonary fibrosis (6 papers, 2010 to 2024). Chronic progressive interstitial lung disorder characterized by the replacement of the lung tissue by connective tissue, leading to progressive dyspnea, respiratory failure, or right heart failure. "Adoptive transfer of nonspecific interstitial pneumonia fibroblasts into SCID mice caused diffuse interstitial fibrosis, and systemic immunoneutralization of CCR7 or Ccl21-attenuated pulmonary fibrosis." (PMID 39768150, 2024). "Therapeutic targeting CCR7 abrogates pulmonary fibrosis induced by the adoptive transfer of human pulmonary fibroblasts to immunodeficient mice." (PMID 34368225, 2021). "Pulmonary fibrosis was induced in CCR7+/+ and CCR7-/- mice via a single intratracheal injection of BLM." (PMID 20815874, 2010). "In IPF, fibroblast overexpression of CCR7, induced by CCL21, suggests a role in pulmonary fibrosis development." (PMID 39768150, 2024). "Fibroblasts expressing CCR7 exhibit activation and chemotactic responses to CCL21, suggesting a role in orchestrating pulmonary fibrosis development." (PMID 39768150, 2024). "Bleomycin-induced pulmonary fibrosis in mice involves CCL21 induction, with chemotactic responses of CCR7+ bone marrow progenitor cells, and Ccr7-/- mice are protected from fibrosis." (PMID 39768150, 2024). "The CCR7/CCL19 axis seemed to play a role in airway smooth muscle hyperplasia in asthmatics and CCR7 was also expressed on fibroblasts in fibrotic areas of idiopathic pulmonary fibrosis patients." (PMID 35137398, 2022). "In the study we report here, we targeted CCR7 in a bleomycin (BLM) model of PF, which has been useful in dissecting the roles of the chemokine/cytokine network in both the inflammatory and fibrogenic phases of lung fibrosis." (PMID 20815874, 2010). "Notably, the pleiotropic activities of homeostatic CXCL12 and CCR7 in IPF encompass chronic lung inflammation, angiogenesis, and fibrosis, indicating diverse chemokine production triggering critical pathways in pulmonary fibrosis." (PMID 39768150, 2024). "In pulmonary fibrosis, a model of exacerbated wound healing, the absence of CCR7 alleviates the disease, and in a skin injury model, fibrocytes are able to migrate to wound sites and enhance healing in a CCR7-dependent manner." (PMID 24205367, 2013).
sarcoidosis (6 papers, 2010 to 2025). Sarcoidosis is a multisystemic disorder of unknown cause characterized by the formation of immune granulomas in involved organs. "Primarily, we noted that the level of CCR7-expressing Tregs decreased in patients with sarcoidosis vs. the control group (65.55% (60.08; 70.60) vs. 76.93% (69.59; 79.86) with p < 0.001)." (PMID 37189479, 2023). "We noted that the level of CCR7-expressing Tregs decreased in patients with sarcoidosis vs. the control group (65.55% (60.08; 70.60) vs. 76.93% (69.59; 79.86) with p < 0.001)." (PMID 37189479, 2023). "Next, a significantly higher proportion of CXCR5-expressing CD45RA − CCR7+ Th cells in patients with sarcoidosis in comparison to the healthy controls was revealed, that represents the expansion of this memory Th cell subset in the disease." (PMID 31974463, 2020). "Of all markers tested the lymph node homing receptor CCR7 and CD15s (sialyl lewis x, expressed by Tregs in sarcoidosis) were lower in MulTreg, whilst gut homing integrin beta 7 (β7) showed a trend for increased expression in MulTreg according to both MFI and frequency." (PMID 34539651, 2021). "Next, to examine the frequencies and distribution of CD4+ T cell maturation subsets in different groups of patients with sarcoidosis, we analyzed CD45RA and CCR7 co-expression on Th cells." (PMID 41376646, 2025). "First we studied the relative gene expression of the typical M1 markers, IL-12p35, IL-23p19, CCR7, and M2 markers, IL-10 and CCR2, in total BAL cells of sarcoidosis patients and healthy subjects after culturing in medium for four or 24 h, or after 24 h of LPS stimulation." (PMID 20813038, 2010).
T cell lymphomas (6 papers, 2010 to 2022). "In T cell lymphoma, higher expression of CCR7 was associated with distant metastasis as well as tumor cell migration in vitro and the underlying mechanism might be associated with PI3K/AKT signaling pathway." (PMID 34544443, 2021). "In a case of primary cutaneous aggressive epidermotropic CD8+ T-cell lymphoma transformation from an indolent to an aggressive phase was accompanied by a shift to CCR7 expression." (PMID 34778050, 2021). "This is the first study analyzing the expression profiles of CCR7 chemokine receptors in a larger series of human T cell lymphoma tissues and cell lines." (PMID 21548969, 2011). "In other, very rare T-cell lymphomas, studies on CCR7 have been sporadically reported." (PMID 34778050, 2021). "Whether PI3K/Akt participates in the invasion and metastasis of T cell lymphomas induced by CCR7 and if a relationship exists between them remains unclear." (PMID 21548969, 2011). "In addition, CCR7 down-regulation is observed in T cell lymphomas when compared with healthy tissue." (PMID 21092185, 2010). "Therefore, the ideal CCL21 concentration for CCR7 expression in T cell lymphoma is 50-100 nmol/L." (PMID 21548969, 2011).
atopic dermatitis (5 papers, 2022 to 2025). "Recently, researchers have identified a small subset of skin DCs called mregDCs with high expressions of BIRC3, LAMP3, IL15, CD40, and CCR7, and this subset has been thought to be associated with wound healing and the exacerbation of atopic dermatitis." (PMID 35280984, 2022).
brain tumors (5 papers, 2019 to 2025). "Taken together, these results suggest that dorsal MLVs mediate the DC trafficking from brain tumors to dCLNs at least in part via the VEGF-C-CCL21/CCR7 signaling pathway." (PMID 32094452, 2020). "Unlike the other tumor types analyzed, T cells infiltrating brain tumors display an effector memory phenotype based on their lack of CCR7 and CD45RA expression." (PMID 31417550, 2019).
Crohn disease (5 papers, 2009 to 2026). A gastrointestinal disorder characterized by chronic inflammation involving all layers of the intestinal wall, noncaseating granulomas affecting the intestinal wall and regional lymph nodes, and transmural fibrosis. "Further, it has been observed that leptin production in mesenteric fat is increased in early Crohn’s disease patients, which has been associated with upregulation of CCR7, maturation and migration of cDCs." (PMID 36248804, 2022). "CC-chemokine receptor 7 (CCR7) has a pathogenic role in Crohn’s disease." (PMID 31614573, 2019). "For example, CCR7 expression on CD83+DC-SIGN+ intestinal cDCs is lower in patients with Crohn’s disease." (PMID 36248804, 2022). "Whether CCR7 expression is timepoint dependent and what effect this has on T cell priming in Crohn’s disease remains to be elucidated." (PMID 36248804, 2022). "Through network analysis, we can introduce IL-7, GATA3, TXN, ETS-1, CCR7, CD28, and CD5 as Crohn’s disease-related critical genes and possible biomarker panel." (PMID 33585004, 2020). "Among the 81 queried DEGs related to Crohn’s disease, 7 genes (IL-7, GATA3, CD28, CD5, TXN, ETS-1, and CCR7) were introduced as dysregulated genes." (PMID 33585004, 2020).
cutaneous melanoma (5 papers, 2014 to 2025). A primary melanoma arising from atypical melanocytes in the skin. "In 38 patients with cutaneous melanoma, CCR7 overexpression was significantly linked to shorter time to progression and survival times, although, interestingly, normal CCR7 levels were associated with elevated overall survival." (PMID 35203305, 2022). "In contrast, it was observed that overexpression of CCR10 and CCR7 resulted in severe outcome of human cutaneous melanoma growth, as determined by high risk of relapse and death of patients." (PMID 27807435, 2016).
ischemic stroke (5 papers, 2022 to 2025). A stroke disorder caused by obstruction of blood flow to the brain, due to thrombotic (local blood clot formation) or embolic (due to a blood clot or other material traveling from another site) event. "The expression of CCR7 was also down-regulated in peripheral blood during the acute phase of ischemic stroke." (PMID 38154101, 2023). "Based on the analysis of direct and total effects, the expression of CCR7 on naive CD8br T cells is negatively correlated with ischemic stroke (total effect β = –0.037, 95% CI: –0.064 to –0.010), with both direct effects A and B being negative, suggesting a potential protective role." (PMID 40620597, 2025).
Lymphadenopathy (5 papers, 2010 to 2024). Enlargement (swelling) of a lymph node. "In B-CLL it appears that CCR7 activity alteration is associated with the formation of proliferative centres and lymphadenopathies." (PMID 21092185, 2010). "Like in the case of the α4β1 integrin, CCR7 overexpression in CLL cells correlates with the presence of lymphadenopathy, and an anti-CCR7 monoclonal antibody inhibits in vitro CLL cell migration and induces complement-dependent cytotoxicity against CLL cells." (PMID 30787933, 2019). "According to our data, anti-CCR7 therapy could also target or avoid CNS infiltration, tackle bulky lymphadenopathies, or prevent T-PLL relapse in settings of minimal residual disease in lymphoid organs or other sites where alemtuzumab is ineffective in tumor cell clearance." (PMID 33110606, 2020). "There is a correlation between CCR7 expression, receptor for both CCL21 and CCL19, and clinical lymphadenopathy, and blocking CCR7 suppresses TEM of CLL cells." (PMID 39876896, 2024).
lymphopenia (5 papers, 2020 to 2024). Reduction in the number of lymphocytes. "Namely, there are significantly increased counts of CD8+CD28-, CD8+CD57+, CD8+CD28-CD57+, CD8+CD45RA+CCR7- cells, despite the observed lymphopenia." (PMID 35615367, 2022). "Some characteristics were observed in all the clusters, such as lymphopenia, an elevated level of effector CD8+CCR7- T cells (with extremely high levels in clusters 4 and 5) and an elevated level of plasmablasts (with extremely high levels in cluster 3)." (PMID 35911748, 2022). "Some characteristics were observed in all the clusters of patients, such as lymphopenia and an elevated level of effector CD8+CCR7- T cells." (PMID 35911748, 2022). "Despite profound lymphopenia, we report a lack of cfDNA released by adaptive immune cells and increased CCR7 expression on T cells indicative of egress out of peripheral blood." (PMID 38299308, 2024). "We demonstrated that the observed lymphopenia postinfusion is due to a combined RMD effect, consisting of (i) apoptosis; (ii) downregulation of cell surface markers CD3, CD4, and CD8; (iii) upregulation of homing markers α4β7, CCR7, and CCR9; and (iv) migration from the periphery to the gut and LNs." (PMID 33362765, 2020).
metastatic tumors (5 papers, 2007 to 2022). "Upregulation level of CCR7 marker has been reported in head and neck tumoral squamous cell 5,6, metastatic tumor cells and regional lymph nodes." (PMID 30233771, 2018). "Expression of chemokines and their receptors, such as CXCL12/CXCR4 and CCL21/CCR7, in both primary and metastatic tumors suggest that chemokine receptor-bearing cells actively enter the circulation and home to metastatic sites." (PMID 25909600, 2015). "Systemic metastatic disease was the first sign of relapse in seven patients (8.3%) and in all cases there was positive immunostaining for CCR7 at presentation." (PMID 17687340, 2007). "Chemokine CCL21 can induce the migration of antigen-presenting dendritic cells from the interstitium to the lymphatic system, and another study indicated that tenascin-C enhanced an immunosuppressive lymphoid stroma through CCL21/CCR7 signaling, leading to an increase in metastatic tumors." (PMID 34177903, 2021). "Indeed, 15% of patients with primary tumours that displayed the highest levels of immunostaining for CCR7 developed systemic metastatic disease." (PMID 17687340, 2007). "When 15×19 CAR T cells were treated with an anti-CCR7 antibody, their cytotoxicity against metastatic tumors was reduced and the number of cells did not increase." (PMID 36618357, 2022).
pulmonary hypertension (5 papers, 2020 to 2022). Increased pressure within the pulmonary circulation due to lung or heart disorder. "Analogously, IL-12p40 serum levels are increased in mice deficient for chemokine receptor CCR7, which develop pulmonary hypertension, pulmonary arterial remodeling, and perivascular lymphoid infiltrates in the lung." (PMID 35757687, 2022). "Of these chemokines and chemokine receptors, Ccl2, Ccl7, Ccl20, Ccl21, Cxcl13, Cxcl4, Ccr6 and Ccr7 have already been demonstrated to be associated with pulmonary hypertension." (PMID 32176619, 2020). "Then, we further assessed the expression of CCR7, let‐7e‐5p and SNHG12 in the Su/Hx‐induced pulmonary hypertension mouse model." (PMID 33630421, 2021). "Moreover, reduced CCR7 level was identified; of note, the lack of CCR7 resulted in the infiltration of perivascular lymphocytes, including B cells, in pulmonary hypertension." (PMID 36277750, 2022).
T-cell acute lymphoblastic leukemia (5 papers, 2013 to 2024). Acute lymphoblastic leukemia of T-cell origin. "Furthermore, CCR7 has been also implicated in acute T-cell leukemia infiltration of the central nervous system (CNS)." (PMID 24305507, 2013). "For this reason, it would be very interesting to identify those malignant hemopathies in which CCR7 expression correlates with CNS infiltration, as it is the case for T-cell acute lymphoblastic leukemia." (PMID 24305507, 2013).
uveitis (5 papers, 2015 to 2025). An inflammatory process affecting a part of or the entire uvea. "In the systemic disease-associated uveitis group, in addition to identifying signaling pathways such as the chemokine receptor CCR7, which is implicated in T cell homing, we detected metaDEGs associated not only with T cell responses, but also with B cell responses." (PMID 40270958, 2025). "Furthermore, there was a significant correlation between patients’ age-specific regulation of genes MYLIP and PDE4A in the uveitis only group and CCR7, LBH, and LCK in the systemic disease-associated uveitis group." (PMID 40270958, 2025). "Anti‐IL‐18R antibody might serve as a potential therapeutic agent for uveitis through its capacity to inhibit CD83+CCR7+NK cells infiltration." (PMID 30548211, 2019). "The increases in IL‐18 observed in EAU might represent an important factor which promotes CD83+CCR7+ NK cell activation, thereby participating in the development of uveitis." (PMID 30548211, 2019). "Overall, distinct clusters of uveitis cases (termed “JIA uveitis 2”) became apparent, characterized by distinct expression of IGHD, CCR7, IGHM and CD27." (PMID 33042130, 2020). "In addition, we examined whether blocking of IL‐18 receptor would alleviate the development of uveitis and affect the status of CD83+CCR7+NK cells, DCs and T cells." (PMID 30548211, 2019).
Allergy (4 papers, 2019 to 2024). An allergy is an immune response or reaction to substances that are usually not harmful. "The amelioration of AAI has already been associated with impaired DC migration and CCR7 expression suggesting that neutralizing DC lung chemotaxis could be beneficial for treatment against allergic diseases in patients." (PMID 39186814, 2024).
Burkitt lymphoma (4 papers, 2011 to 2024). A rare form of malignant mature B-cell non-Hodgkin lymphoma. "C-C chemokine receptor 7 (CCR7) was the first lymphocyte-specific G protein-coupled receptor (GPCR) identified and was originally named Epstein–Barr virus (EBV)-induced gene 1 (EBI1) since it was upregulated in EBV-infected Burkitt’s lymphoma B cells." (PMID 35203305, 2022). "The human Burkitt's lymphoma cell line NC-37, which expresses CXCR4, CXCR5, CXCR7 and CCR7, was selected as a model system." (PMID 21672222, 2011).